RPS19 (ribosomal protein S19)
Diseases named in the same sentence as RPS19 in open-access papers (continued):
Sharing a sentence is not in itself a finding about the gene and the disease.
cancer (continued). "Finally, TNFSF10—TNFRSF10B (TRIAL—TRIAL-R), SIRPA—CD47 (“don't eat me”), C5AR1—RPS19, and GAS6—AXL act as negative regulators of the innate immune system by inhibiting cytokine responses, phagocytosis of cancer cells, and promoting the immunosuppressive TME." (PMID 37823774, 2023). "In so doing it might interfere with incorporation of RPS19 into the ribosome and could explain why knocking down RPS19 and DAP treatment had the same qualitative outcome for cancer cells." (PMID 28680364, 2016).
tumor (26 papers, 2016 to 2025). "Subsequent reports have indicated that C5aR1 expressed on MDSCs can also impair anti-tumor T cell responses by binding to ribosomal protein S19 (RPS19)." (PMID 39958348, 2025). "In particular, one pair of ligands and receptors (C5AR1 and RPS19) was inferred to play key roles in the crosstalk of stroma and tumor regions." (PMID 38729966, 2024). "C5AR1 and RPS19 were highly expressed in tumor tissue compared with normal tissue in the TCGA-CRC and TCGA-ESCA datasets." (PMID 38002057, 2023). "One study reveals that RPS19 expression in tumor cells promotes infiltration of regulatory T cells and reduces infiltration of CD8+ T cells into tumors by interaction with C5AR1 in myeloid-derived suppressor cells." (PMID 38002057, 2023). "Tumors secrete various factors which promote the accumulation of heterogeneous population of TAMs, MDSCs and immunosuppressive protein RPS19 in the tumor microenvironment." (PMID 34068008, 2021). "LE-KLK4 also expressed RPS19, with monocyte-recruiting activity, and this too was reduced in tumor samples." (PMID 34936871, 2021). "In line with the IHC results, Western blot analysis also showed a reduction in the expression of RPS19 with atovaquone treatment in HCC1806 tumor lysates." (PMID 34068008, 2021). "It was also noted that reducing RPS19 in tumor cells or blocking the C5AR1-RPS19 interaction decreases RPS19-mediated immunosuppression, impairing the tumor growth." (PMID 33155039, 2020). "Many proteins involved in tumour cell differentiation, such as ribosomal protein 19 (RPS-19), lamin A/C (LMNA) and immunoglobulin heavy constant mu (IGHM), exhibited decreased expression upon cell treatment with activated PSC secretome." (PMID 30923340, 2019). "C5aR1 expressed on MDSCs is also able to bind ribosomal protein S19 (RPS19), which is released from apoptotic tumor cells into the tumor microenvironment, leading to a shift toward Th2 cell responses with increased levels of immunosuppressive TGF-β." (PMID 31001273, 2019). "RPS5 in combination with RPS19 (for tumor tissues) or HNRNPH (for cell lines) showed the highest expression stability compared to other genes such as B2M and GAPDH, which are the most commonly used reference genes in many human and canine OS studies to date." (PMID 29178874, 2017). "Therefore, reducing its level in tumor cells should impede the development of tumors by decreasing RPS19 mediated immunosuppression." (PMID 34068008, 2021). "RPS19 interacts with C5aR1 expressed on tumor infiltrating MDSCs." (PMID 34068008, 2021). "Lastly, we validated the expression of the five RBRS genes (RPL38, RPS2, RPS14, RPS19, and RPS28) using qRT-PCR on tumor and adjacent normal samples from 12 ccRCC patients at Meizhou Hospital." (PMID 40642093, 2025). "Atovaquone (ATQ) reduces the expression of RPS19, MDSCs, Tregs and immunosuppressive cytokines IL-10 and TGF-β in tumor cells." (PMID 34068008, 2021). "RPS6, RPS19 and RPS25 helps in the transcription initiation of viral genes while RPL5 and RPL11 acts as tumor suppressors by degrading the mRNA of c-myc, through RNA induced silencing complex (RISC)." (PMID 29568375, 2018). "Furthermore, we inferred the important interaction between tumor and stromal regions mediated by gene pair of C5AR1 and RPS19, which played roles of ligand and receptor, respectively." (PMID 38729966, 2024). "In addition, atovaquone suppressed MDSCs and Tregs in blood and tumor cells with a reduction in immunosuppressive cytokines TGF-β, IL-10 and RPS19." (PMID 34068008, 2021). "Ribosomal protein S19 (RPS19), upon release from dying tumor cells, interacts with C5aR1 expressed on MDSCs, promoting its recruitment to tumors, the generation of Tregs, the production of immunosuppressive cytokines (including TGF-β), and the reduction of CD8+ T-cell tumor infiltration." (PMID 31031765, 2019). "(B) Each cell is colored according to expression value of the genes RPS19 and C5AR1 in tumor and non-tumor cells, respectively." (PMID 33155039, 2020).
infection (3 papers, 2016 to 2024). The state of being infected such as from the introduction of a foreign agent such as serum, vaccine, antigenic substance or organism. "In addition, we validated the relative expression of some of the Rpl and Rps transcripts by RT-PCR and found the significantly lowered expression of Rpl4, Rpl12, Rps18, Rps19 during the infection compared to naïve animals." (PMID 35789215, 2022).
adenocarcinoma (1 paper, 2022). A common cancer characterized by the presence of malignant glandular cells. "The activity of six ligands expressed in multiple cell types indicated that RPS19 was overexpressed in adenocarcinoma." (PMID 35954218, 2022). "When the ligand-target links between adenocarcinoma and macrophages were investigated, we identified CALM1, RPS19, GSTP1, and LGALS3 as prioritized adenocarcinoma expressed ligands." (PMID 35954218, 2022).
muscular disorders (1 paper, 2013). "We found that genes enriched in the functions of hematological systems, nervous system development and skeletal and muscular disorders had significant differential expression in RPS19 MO embryos compared with controls." (PMID 23990987, 2013).
RPS19 also shares sentences with these, for which no sentence is quoted: myelodysplastic syndrome (3 papers); Bloom syndrome (2); dyskeratosis congenita (2); hematologic malignancies (2); nerve sheath tumors (2); Pancytopenia (2); Werner syndrome (2); acute myeloid leukemia (1); aplastic anemia (1); atherosclerosis (1); beta thalassemia (1); Bochdalek hernia (1); cartilage-hair hypoplasia (1); cerebellar ataxia (1); chronic myeloid leukemia (1); Cohen syndrome (1); congenital anemia (1); congenital dyserythropoietic anemia type 2 (1); congenital neutropenia (1); developmental delay (1); Familial adenomatous polyposis (1); Fanconi anemia (1); gangrene (1); genetic disorders (1); haemochromatosis (1); HCMV infection (1); heart failure (1); hereditary thrombocytopenia (1); human papilloma virus infection (1); inflammatory bowel disease (1).
A further 24 diseases each share a sentence with RPS19 in 1 paper.